BRCA1 (BRCA1 DNA repair associated)
Diseases named in the same sentence as BRCA1 in open-access papers (continued):
Sharing a sentence is not in itself a finding about the gene and the disease.
breast cancer (continued). "In contrast, PKM2 deficiency without disrupting PKM1 accelerated breast cancer formation in a mouse model of BRCA1 deficiency." (PMID 33292198, 2020). "Our study of 3877 mutation carriers with 426 incident breast cancer cases is the largest prospective cohort to date and the first prospective study investigating breast cancer risk after RRSO for BRCA1 and BRCA2 mutation carriers in the context of menopausal status." (PMID 31948486, 2020). "To test if 53BP1 loss can also promote the growth of tumors with diminished BRCA1 expression, we ranked breast cancer samples in TCGA database based on BRCA1 expression levels and compared 53BP1 expression levels between BRCA1-low (lowest 10%) and BRCA1-high (highest 10%) samples." (PMID 32139898, 2020). "Therefore, further studies are needed to link the role of BRCA1 in maintaining genomic stability with breast cancer." (PMID 32013256, 2020). "BRCA1-defective breast cancers are usually high grade and have poor prognoses." (PMID 32591500, 2020). "From a biochemical perspective, the two best-characterized mutations found in breast cancer, if heterozygous, would not be expected to disrupt the working, wild-type BRCA1-A, similar to many known BRCA1 mutations." (PMID 33142801, 2020). "In sporadic breast cancer, the frequency and relevance of BRCA1: p.Ile1845fs variant has not been elucidated completely." (PMID 31908633, 2020). "BRCA1 levels are normally elevated in tumor biopsies from breast cancer patients who do not carry a germline mutation in the BRCA122." (PMID 33277540, 2020). "Morphological and molecular features of BRCA1 and BRCA2-associated breast cancer." (PMID 33117676, 2020). "Some BRCA1 and BRCA2 mutations that are inherited increase breast cancer risk in women." (PMID 32824813, 2020). "Thus, their findings indicate that resveratrol prevents breast cancer development by modulating BRCA1 expression via AhR signaling regulation." (PMID 32183060, 2020). "Since most symptomatic patients are tested for NF1 mutations before they visit a breast cancer clinic, these patients are not tested for mutations in BRCA1/2 genes for their breast disease, a requisite for enrollment in the current study." (PMID 32566746, 2020). "In Anglian and US non-Hispanic white families, the frequency of pathogenic BRCA1/2 variants range between 1:400 and 1:500 in the general population, while the highest observed frequency is about 1:40 in the Ashkenazi-Jewish community." (PMID 33716731, 2020). "The HMMR-BRCA1 interaction influences mammary tumorigenesis as indicated by the association between HMMR polymorphisms and breast cancer risk in carriers of BRCA1 mutations but not BRCA2 mutations." (PMID 32231069, 2020). "Mutations of the BRCA1 and MYC genes exacerbate breast cancer." (PMID 33324444, 2020). "In breast cancer, the absolute risk increase in carriers of BRCA1 and BRCA2 pathogenic variants depends on breast cancer polygenic risk scores, which might influence clinical decision-making." (PMID 32423490, 2020). "The RAD52 S346X allele was associated with a reduced risk of developing breast cancer in BRCA2 carriers [per‐allele hazard ratio (HR) = 0.69, 95% confidence interval (CI) 0.56–0.86; P = 0.0008] and to a lesser extent in BRCA1 carriers (per‐allele HR = 0.78, 95% CI 0.64–0.97, P = 0.02)." (PMID 32175645, 2020).
breast cancer (continued). "Studies have estimated that the penetrance of BRCA1 and BRCA2 gene mutations are association with the incidence of breast cancer only in 6%–8% of all breast cancer cases, and the cumulative incidence of sporadic breast cancer in approximately 90%–95% of the general population." (PMID 33180852, 2020). "A precision medicine strategy to target different drivers of each individual is highly recommended in the treatment of BRCA1-deficient breast cancer, especially for those patients who do not respond to PARPi10–12." (PMID 32978388, 2020). "They found that pathogenic CHEK2 variants were the third most frequent germline alterations in both cancers (following BRCA1/BRCA2 variants); however, CHEK2 significantly prevailed in whites over blacks in both breast cancer (2.3% vs. 0.15%) and ovarian cancer (1.3% vs. 0%)." (PMID 33322746, 2020). "PARP inhibitors have been approved for the treatment of BRCA1/2 mutant ovarian and breast cancers." (PMID 32171277, 2020). "Because of bilateral breast cancer, she underwent BRCA1 and BRCA2 testing." (PMID 32455662, 2020). "BRCA1 is a crucial factor involved in breast cancer metastasis." (PMID 33324542, 2020). "BRCA1 and BRCA2 are two major genes associated with a lifetime risk of 50%–80% of breast cancer." (PMID 32959997, 2020). "Few clinical and molecular factors have been studied, such as CD133 overexpression and platinum resistance, overexpression of MDR-1 (multi drug resistance 1), having suffered from a previous breast cancer, loss of BRCA function and, presence of mutations in BRCA1 and BRCA2 genes." (PMID 32366278, 2020). "Of those, 597 BRCA1 and 249 BRCA2 mutation carriers were diagnosed with breast cancer." (PMID 32140806, 2020). "SBBC patients with a family history of breast cancer or bilateral ER-negative disease had a higher frequency of BRCA1/2 mutations than the cohort without a history of these conditions." (PMID 32117708, 2020). "Several cell lines, such as COLO320DM (colon cancer) and SKOV3 (ovarian), cluster near UWB1.289 + BRCA1 and demonstrate a drug sensitivity signature similar to the BRCA1-restored cell line, whereas OCUBM (breast cancer) and CAOV3 (ovarian) behave like BRCA1-deficient UWB1.289." (PMID 32198459, 2020). "However, we did not detect any clear relevant variant in 23 genes out of 26, indicating that BRCA1 and BRCA2 are probably the most commonly mutated genes associated with breast cancer predisposition in African women." (PMID 32959997, 2020). "To establish the effect of BRCA1 on inflammasome activation in mammary cells, we analyzed IL‐1β secretion and caspase 1 activation in MCF10A cells with detectable inflammasome‐associated components, compared to several breast cancer cell lines." (PMID 32195105, 2020). "Contralateral breast cancer is also increased in BRCA1 and BRCA2 PV carriers." (PMID 32045981, 2020). "When assessed by BRCA1/2 pathogenic germline gene variant, a significant association was observed between weight loss of ≥10 pounds and reduced risk of breast cancer among women with BRCA1 but not BRCA2 pathogenic germline gene variant." (PMID 32165993, 2020). "For example, in breast cancer, TRβ protein positivity was associated with better 5-year survival in BRCA1 mutated cancers but not in sporadic breast cancers." (PMID 32894083, 2020). "FANCA variants are a significant risk factor for breast cancer among the population without BRCA1/2 loss." (PMID 31931827, 2020). "BRCA1/2 negativity was identified in 92.88% accuracy with no need for BRCA1/2 gene testing within minutes in high-risk breast cancer patients using this algorithm and stress of waiting for the test result; time and money loss were prevented." (PMID 33488844, 2020). "A relevant risk elevating effect of OC use for breast cancer is so far not proven but especially in the specific age group of young BRCA1/2 mutation carriers before the age of 40 years is still possible." (PMID 32140806, 2020).
breast cancer (continued). "Moreover, it is known that pre-invasive lesions, such as DCIS, are common in BRCA-associated breast cancers and that in high-risk women with DCIS, the prevalence of a BRCA1/2 mutation is high." (PMID 32333294, 2020). "Such an independence of BRCA1 mutation role was confirmed by the comparison of this study group with the group of patients without BRCA mutations treated for breast cancer." (PMID 31872386, 2020). "For instance, we detected BRCA1 in Breast Cancer, Amyloid Precursor Protein (APP) in Alzheimer’s Disease, INS in A1C measurement and Type 2 Diabetes, PCSK9 in LDL cholesterol levels and SNCAIP in Parkinson’s Disease, and the circadian rhythm gene CRY2 in Morning vs. Evening chronotype." (PMID 32678846, 2020). "The study included 258 BRCA1 and 108 BRCA2 mutation carriers with a history of breast cancer." (PMID 32140806, 2020). "Considering the crucial role of BRCA1/2 in breast cancer suppression, due to their function in maintaining genome integrity through protein synthesis required for repairing DNA damage, both BRCA genes play parts in apoptosis and the processes of tumor suppression." (PMID 33194751, 2020). "Among Hispanic populations from Iberia and the Americas, BRCA1 c.3331_3334delCAAG (Breast Cancer Information Core designation: 3450del4 or rs80357903) is one of the most widely distributed founder mutation and reaches its highest frequency in admixed populations from Central Colombia." (PMID 33087180, 2020). "The extent of concordance between synchronous bilateral breast cancer (SBBC) tumors with respect to hormone receptor expression and BRCA1/2 mutations is unknown." (PMID 32117708, 2020). "Such mutant BRCA1 protein may be stabilized by the heat shock chaperone HSP90 as shown in MDA-MB-436 breast cancer cells." (PMID 32029455, 2020). "The 10-year cumulative contralateral breast cancer risk following the initial breast cancer diagnosis was 21.1% for BRCA1, 10.8% for BRCA2 and 5.1% for non-carriers." (PMID 31935898, 2020). "Similarly, resveratrol was shown to inhibit DNMT1 activity and expression at the BRCA1 promoter, leading to promoter hypomethylation and the reactivation of BRCA1 in breast cancer cells." (PMID 32878338, 2020). "Using G2 micronucleus assay and G2 chromosomal assay, most studies have reported the lymphocyte of healthy carriers with BRCA1 mutation are hypersensitive to invitro ionizing radiation compared to non-carriers without a history of breast cancer." (PMID 33013205, 2020). "Women with a BRCA1 and BRCA2 mutation and other women with a family history of breast cancer risk may choose to undergo bilateral prophylactic mastectomy." (PMID 32471217, 2020). "Full sequencing (in particular, using gene panels including BRCA1/2) is warranted in women with early-onset breast cancer, in particular for those with a positive family history and those with breast cancers with clinical features characteristic of BRCA1-related tumors." (PMID 32824581, 2020). "Inactivation of BRCA1 in a porcine mammary cell line does result in a transformed phenotype resembling human breast cancer, suggesting that the pig is a suitable species to model breast cancer, but a representative pig model has yet to be produced." (PMID 31940967, 2020).
breast cancer (continued). "The breast cancer surveillance guidance for BRCA mutation carriers from the NABON specifies that screening for ovarian cancer in BRCA1 and BRCA2 mutation carriers is not recommended." (PMID 32655641, 2020). "This phenomenon suggested that BRCA1 c.3257del might contribute to breast cancer development with a specific ER/PR status." (PMID 32879886, 2020). "It is still debated whether BRCA1- and BRCA2-deficiency, which causes genomic instability and increased tumor burden, could increase immunosensitivity in breast cancer and predict clinical benefit from immunotherapy." (PMID 32892748, 2020). "Several studies have investigated prognosis among BRCA1/2 mutation carriers and noncarriers, but the prognostic impact on outcomes of breast cancer patients has not been definitely determined." (PMID 32322271, 2020). "BRCA1 and BRCA2 carrier tumors have characteristic mutation profiles, accompanied by homologous recombination deficiency, which distinguishes these from unselected breast carcinomas on a molecular level." (PMID 32964118, 2020). "Among variant-positive males (N = 81), 2 (2.5%) had breast cancer (BRCA1 c.5266dupC and BRCA2 c.4471_4474delCTGA) and 6 (7.4%) had prostate cancer (two men with BRCA1 c.5266dupC and one man each with BRCA1 c.68_69delAG, BRCA2 c.2808_2811delACAA, BRCA2 c.5946delT, and BRCA2 c.4716_4717delinsAAAGACC)." (PMID 31892343, 2019). "Women carrying an inherited BRCA1 or BRCA2 mutation experience similar severity, frequency, and timing of hematologic toxicity as women without a germline mutation while receiving modern day chemotherapy and supportive care for localized breast cancer." (PMID 31407530, 2019). "Here we used the results of genetic testing of women diagnosed with breast cancer, but who did not have variants in BRCA1 and BRCA2 genes." (PMID 31569399, 2019). "Polymorphisms within two DNA double-strand break repair genes, XRCC3 c.722C>T (rs861539) and RAD51D c.698A>G (rs28363284), were assessed for their association with breast cancer risk in high-risk families in Chile without known BRCA1/2 mutations." (PMID 30781715, 2019). "One of the leading compounds—adenosine 5’-monophosphate (A5MP) was able to halt the proliferation of BRCA1-deficient HCC1937 breast cancer cells and did not influence cells with restored BRCA1 expression." (PMID 31615159, 2019). "In liver cancer cells, transforming growth factor beta 1 (TGF-β1) indirectly promotes epithelial-mesenchymal transition (EMT) and CSC phenotypes through down-regulation of TP53INP1 by miR-155 while in breast cancer, miR-155 is involved in tumor initiation via transcriptional repression of BRCA1." (PMID 31137686, 2019). "BRCA2-deficient breast cancers displayed similar features of genomic instability as that in BRCA1-deficient breast cancers but did not demonstrate similar immunophenotype as that of BRCA1-deficient breast cancers." (PMID 31022191, 2019). "Therefore, we sought to examine the therapeutic effects of mTOR inhibition in relation to BRCA1 expression in breast cancer cell lines." (PMID 31771139, 2019). "Further profiling of the ‘CIN25’ signature, a gene expression signature for chromosomal instability, in breast cancers from WSI and TCGA showed that BRCA1- and BRCA2-deficient breast cancers generally overexpressed this gene set compared to BRCA-proficient breast cancers." (PMID 31022191, 2019). "Although risk for developing specific subtypes of breast cancer was not evaluated for this SNP, the link between BRCA1 dysfunction and TNBC warrant further investigation." (PMID 31379942, 2019).
breast cancer (continued). "The first study investigating FANCC germline mutations enrolled 88 BRCA1/2-negative familial breast cancer patients from the United Kingdom, finding no deleterious mutations by conformation sensitive gel electrophoresis followed by a sequencing assay." (PMID 30967997, 2019). "Given its ability to interact with HDACs34, BRCA1 might synergize with SAHA to create significant epigenetic stresses, which results in the loss of breast cancer cell stemness." (PMID 31273285, 2019). "Loss of BRCA1 and BRCA2 function has already been well established in breast cancer." (PMID 31225499, 2019). "We asked whether the BRCA1 status would affect breast cancer cell stemness under hypoxic conditions." (PMID 31273285, 2019). "We organized familial pedigrees of 2555 patients with breast cancer who underwent genetic screening for BRCA1/2 in Samsung Medical Center between January 2002 and May 2018." (PMID 30622657, 2019). "Analysis of the data obtained in our study suggests that the increase in the activity of Px in the saliva of BRCA1+ patients with breast cancer indicates an intensified enzymatic antioxidant defence, protecting against oxidative damage to salivary glands and the entire oral cavity." (PMID 31597313, 2019). "The frequency and spectrum of BRCA1/2 LGRs in familial breast cancer patients from China mainland remain largely unknown." (PMID 31174498, 2019). "The carriers of these gross duplications were most frequently affected with unilateral breast cancer and the only genotype–phenotype correlation was the presence of a larger proportion of triple-negative breast cancer in the cohort of BRCA1 gross duplication carriers." (PMID 30054569, 2019). "We also developed a model without BRCA1/2 mutation status (PredictCBC-1B) since this information was available for only 6% of patients and is routinely unavailable in the general breast cancer population." (PMID 31847907, 2019). "Unlike breast cancer, which has a well-established association with mutations in the BRCA1 and BRCA2 genes, there remains insufficient evidence linking genetic variations to the development of PT." (PMID 31195364, 2019). "BRE09-146 (NCT01074970) was a post-neoadjuvant clinical trial for patients with chemoresistant triple-negative or BRCA1/2-mutated hormone receptor (HR)-positive breast cancer." (PMID 31383035, 2019). "Also, hypoxia has been shown to represses the expression of many DNA repair genes including the tumor suppressor gene – BRCA1, which has the important role in preventing the formation of breast cancer." (PMID 30842790, 2019). "The lifetime risk of breast cancer in female germline BRCA variant carriers is up to 85%; the lifetime risk of ovarian cancer is up to 50% Genetic alterations in the BRCA1/2 genes cause over 90% of cases of HBOC." (PMID 31346352, 2019). "In addition, PI3K p110α inhibition was found to render BRCA1-proficient tumours sensitive to the anti-cancer effects of olaparib using a murine breast cancer model." (PMID 31374917, 2019). "For deleterious BRCA1/2 or other HBOC-related mutation carriers, genetic counseling and prophylactic risk-reduction treatment under certain indications will be greatly beneficial in decreasing the incidence of ovarian and breast cancer." (PMID 31472684, 2019). "PARP inhibitors have been proven clinically efficacious in platinum-responsive ovarian cancer regardless of BRCA1/2 status and in breast cancers with germline BRCA1/2 mutation." (PMID 30755715, 2019). "Together, BRCA1 and BRCA2 mutations account for about 5 to 10 percent of all breast cancers." (PMID 30956778, 2019). "Interestingly, hypoxia significantly blocked HDAC inhibitor-induced differentiation, especially, of the BRCA1-competent breast cancer cells." (PMID 31273285, 2019). "A germline mutation in BRCA1 or BRCA2 genes is known to be associated with a much higher than average lifetime risk (72% for BRCA1 and 69% for BRCA2 mutation carriers) of developing breast cancer." (PMID 31182087, 2019).